LRRC3 (leucine rich repeat containing 3)
Synonyms: C21orf102; DKFZP434C128; C21orf30; LRRC3DN
Tractability: Antibody: UniProt predicts a signal peptide or a membrane-spanning region; its Gene Ontology location is reachable by antibodies, with medium confidence. PROTAC: ubiquitination databases record sites on it.
Gene: Protein-coding gene on chromosome 21 (44,455,490 to 44,462,196, forward strand). Ensembl gene ENSG00000160233.
Subcellular location: Membrane
Gene Ontology:
Molecular function: protein binding
Cellular component: plasma membrane; membrane
Genetic constraint (gnomAD): Loss-of-function variants: 6 observed, 5.03 expected, observed/expected ratio (o/e) 1.19, 90% interval 0.63 to 1.88. That is too few expected variants to judge how well the gene tolerates losing a copy. Missense variants: 351 observed, 363.6 expected, observed/expected ratio (o/e) 0.97, 90% interval 0.88 to 1.05. Synonymous variants: 172 observed, 162.36 expected, observed/expected ratio (o/e) 1.06, 90% interval 0.94 to 1.2.
Homologues: Orthologues: chimpanzee LRRC3 (99% identical), macaque LRRC3 (96% identical), pig LRRC3 (82% identical), rat Lrrc3 (81% identical), mouse Lrrc3 (80% identical), rabbit LRRC3 (79% identical), guinea pig LRRC3 (78% identical), tropical clawed frog lrrc3 (58% identical), zebrafish lrrc3 (52% identical). Paralogues in human: LRRC3B (45% identical), LRRC3C (38% identical), VASN (27% identical), TLR8 (22% identical), RXFP2 (22% identical), TLR6 (21% identical), RXFP1 (21% identical), TLR3 (21% identical), LRRC32 (20% identical), TLR1 (19% identical), TLR7 (19% identical), TLR10 (18% identical), and 10 more.
Diseases named in the same sentence as LRRC3 in open-access papers:
LRRC3 is named in the same sentence as 11 diseases in open-access papers, as found by Europe PMC text mining. Sharing a sentence is not in itself a finding about the gene and the disease. The quoted sentences say what the papers report.
lung adenocarcinoma (1 paper, 2018). A carcinoma that arises from the lung and is characterized by the presence of malignant glandular epithelial cells. "Similarly, our mRNA expression signature in EGFR-mutated tumors included DUSP4, EGFR, TNFRSF10B, and LRRC3, all reportedly deregulated in EGFR-mutated lung adenocarcinoma." (PMID 30404194, 2018).
cancer (2 papers, 2015 to 2021). A tumor composed of atypical neoplastic, often pleomorphic cells that invade other tissues. "In vehicle-treated mice we found consistent upregulation of St3gal6, a sialyltransferase associated with immune cell trafficking and worse outcomes in different models of cancer, and Lrrc3, a leucine rich repeat containing protein." (PMID 34281628, 2021).
LRRC3 also shares sentences with these, for which no sentence is quoted: infection (3 papers); allergic disease (1); asthma (1); atherosclerosis (1); hepatic carcinoma (1); hepatic disease (1); metabolic syndrome (1); sickle cell disease (1); tumor (1).